ELOVL2 (ELOVL fatty acid elongase 2)
Diseases named in the same sentence as ELOVL2 in open-access papers (continued):
Sharing a sentence is not in itself a finding about the gene and the disease.
neuroblastoma (5 papers, 2019 to 2025). Neuroblastoma (NB) is the most common solid, extracranial childhood tumor. "In our experiments, the data on ELOVL2 presented here identify that declined DHA synesis caused by MYCN-mediated ELOVL2 inhibition in neuroblastoma cells contributes to tumor aggressiveness." (PMID 31856871, 2019). "In primary neuroblastomas, high expression levels of ELOVL2, which encodes DHA synesis enzyme, correlated with a established favorable clinical and molecular characteristics of tumor biology and indicates a favorable patient survival." (PMID 31856871, 2019). "In contrast, ELOVL2 overexpression exerts tumor-suppressive effects in neuroblastoma by inhibiting cellular proliferation." (PMID 40552308, 2025). "Enforced ELOVL2 expression in MYCN-amplified neuroblastoma cells led to decreased cell growth and counteracted the growth-promoting effect of MYCN overexpression both in vitro and vivo." (PMID 31856871, 2019). "We assessed the expression of ELOVL2 in primary neuroblastomas and neuroblastoma cell lines and unravelled its tumor suppressor activity." (PMID 31856871, 2019). "In line with the mRNA expression level after MYCN depletion, the protein level of ELOVL2 was also upregulated in both neuroblastoma cell lines." (PMID 31856871, 2019). "The tumor suppressive function of ELOVL2 in preclinical neuroblastoma models prompted us to decipher the transcriptional regulation of ELOVL2." (PMID 31856871, 2019). "By IHC analysis of a tissue chip, we compared the difference in ELOVL2 protein expression in normal nerve tissues and neuroblastoma specimens with different international neuroblastoma staging system (INSS) stages." (PMID 31856871, 2019). "In conclusion, MYCN recruits the PRC1 complex, co-occupies the ELOVL2 promoter, mediates H2AK119ub and suppresses its transcription in neuroblastoma cells." (PMID 31856871, 2019). "Our studies also verified that SREBP1 is a transcriptional activator of ELOVL2 in neuroblastoma cells." (PMID 31856871, 2019). "Of all seven known DHA synthesis and transporter genes, the decrease of ELOVL2 expression was mostly significant in MYCN amplified neuroblastoma." (PMID 31856871, 2019). "We further reanalysed RNA-sequencing data from a series of neuroblastomas cohort and draw the same conclusion that ELOVL2 expression was significantly correlated with MYCN status." (PMID 31856871, 2019). "SREBP1 was a known transcription factor that activated ELOVL2 expression, which was further verified by ChIP-qPCR, a luciferase assay and a Western blot in the neuroblastoma cells SK-N-AS." (PMID 31856871, 2019). "Here, we discovered that MYCN inhibition lead to significant DHA accumulation and upregulated its synthesis enzyme ELOVL2 in neuroblastoma cell lines." (PMID 31856871, 2019). "In primary neuroblastoma, high ELOVL2 transcription correlated with favorable clinical tumor biology and patient survival." (PMID 31856871, 2019). "The expression level of ELOVL2 in neuroblastomas from the 496-tumor cohort was significantly correlated with MYCN status." (PMID 31856871, 2019). "ELOVL2 (Elongation Of Very Long Chain Fatty Acids Protein 2) is widely considered a biomarker for aging and silencing by DNA methylation and has been occasionally described in the context of oncogenesis, e.g., in breast and renal cell cancer or neuroblastoma." (PMID 35445910, 2022). "Taken together, ELOVL2 inhibits neuroblastoma growth in vivo and could be regarded as a favorable marker." (PMID 31856871, 2019). "ELOVL2 Knockdown showed the opposite effect in MYCN single-copy neuroblastoma cells." (PMID 31856871, 2019). "To further explore the clinical feature of ELOVL2 in neuroblastoma, we assessed whether ELOVL2 is differentially expressed in primary tumors." (PMID 31856871, 2019).
neuroblastoma (continued). "Given the known metabolic reprogramming in castration-resistant progression and the context-dependent roles of ELOVL2 across cancers (oncogenic in renal carcinoma vs. tumor-suppressive in neuroblastoma), we hypothesized that ELOVL2 may exhibit stage-specific functional plasticity in PCa." (PMID 40552308, 2025). "Therefore, ELOVL2 possesses anti-tumor properties in neuroblastoma cells via DHA synthesis." (PMID 31856871, 2019). "ELOVL2 inhibited cell proliferation and the colony formation of MYCN-amplified neuroblastoma cell lines and mice xenografts, demonstrating that ELOVL2 suppresses critical malignancy processes." (PMID 31856871, 2019). "ELOVL2 expression is relatively lower in neuroblastoma than in normal nerve tissues and negatively correlated with INSS stage." (PMID 31856871, 2019). "Furthermore, we elucidated the upstream epigenetic repressive regulation of ELOVL2 through MYCN and PRC1 complex-mediated histone ubiquitination in MYCN-amplified neuroblastoma." (PMID 31856871, 2019).
renal cell carcinoma (5 papers, 2022 to 2025). "Of note, elevated ELOVL2 expression levels were observed in renal cell carcinoma and significantly associated with a poor prognosis of patients with renal cell carcinoma." (PMID 35853971, 2022). "In renal cell carcinoma, elevated ELOVL2 expression correlates with poor prognosis and promotes tumor progression through anti-apoptotic mechanisms." (PMID 40552308, 2025). "The elongation of very long-chain fatty acid 2 factors (ELOVL2) has been pointed to be elevated in renal cell carcinoma (RCC) patients’ tissue, making it a potential target for therapy." (PMID 36139356, 2022).
age-related macular degeneration (4 papers, 2020 to 2025). Age-related loss of vision in the central portion of the retina (macula), secondary to retinal degeneration. "Furthermore, restoration of mitochondrial activity can rescue age-related macular degeneration (AMD) phenotypes induced by Elovl2 deficiency in human retinal pigmental epithelial (RPE) cells; this indicates a conservative mechanism in both human and mouse." (PMID 35610223, 2022). "Finally, we find deposits underneath the retinal pigment epithelium in Elovl2 mutant mice, containing components found in human drusen, a pathologic hallmark of age related macular degeneration." (PMID 31943697, 2020). "For instance, ELOVL2 deficiency has been linked to age-related macular degeneration phenotypes in human retinal pigment epithelium cells, suggesting that methylation patterns may be influenced by underlying age-related conditions, potentially affecting prediction accuracy in older individuals." (PMID 40244262, 2025). "ELOVL2 has been reported to play a role in retinal physiology and age-related macular degeneration." (PMID 36964402, 2023).
colorectal cancer (4 papers, 2019 to 2025). A primary or metastatic malignant neoplasm that affects the colon or rectum. "The methylation of ELOVL2 accelerates aging in the mouse retina and has been linked to an increased risk of breast and colorectal cancer." (PMID 40558830, 2025). "ELOVL2 has been linked to cancer progression in colorectal cancer and prostate cancer." (PMID 37981715, 2023). "In colorectal cancer, ELOVL2 expression is associated with tumor growth and metastasis." (PMID 37981715, 2023). "Moreover, DNA methylation at ELOVL2 is statistically significantly associated with high-risk future breast and male colorectal cancer development." (PMID 31856871, 2019).
infertile (4 papers, 2014 to 2025). "Accordingly, the body of literature reports that both FADS2 and ELOVL2 knockout male mice are infertile since they cannot sustain sufficient levels of DHA, n-6 DPA and other PUFAs in the testis." (PMID 35173269, 2022). "In our study, we sought to investigate the possible involvement of the ELOVL2, TRIM59, C1orf132, FHL2, and KLF14 genes in reproductive aging, infertility, and outcomes of ART." (PMID 40558830, 2025).
Alzheimer disease (3 papers, 2023 to 2025). A progressive, neurodegenerative disease characterized by loss of function and death of nerve cells in several areas of the brain leading to loss of cognitive function such as memory and language. "Alterations in the ELOVL2 methylation status have been observed in patients in the early stages of Alzheimer’s disease." (PMID 40558830, 2025). "Among other potential applications, this epigenetic marker can be used for predicting the development of neurodegenerative diseases, as alterations in the ELOVL2 methylation status have been observed in patients at early stages of Alzheimer’s disease." (PMID 40244262, 2025).
hepatocellular carcinoma (3 papers, 2016 to 2019). A malignant tumor that arises from hepatocytes. "For example, in hepatocellular carcinoma, a high level of ELOVL2 was significantly associated with poor hepatocellular carcinoma (HCC) prognosis." (PMID 31856871, 2019). "ELOVL5 knockdown experiments also significantly decreased the majority of the elongation capacity of 18-carbon PUFAs in HepG2 hepatoma cells, despite the fact that these cells also express ELOVL2." (PMID 30293059, 2018). "ELOVL2 was found to be up-regulated in hepatocellular carcinoma." (PMID 26862848, 2016).
metabolic syndrome (3 papers, 2014 to 2022). A cluster of metabolic risk factors for CARDIOVASCULAR DISEASES and TYPE 2 DIABETES MELLITUS. "Up-regulation of the ELOVL2 gene involved in fatty acid elongation is a strong link to lipid metabolism, and may help explain the connection between DDTs and metabolic syndromes reported in people." (PMID 30307967, 2018). "Finally, relatively recent studies suggest that impaired Elovl2 expression is highly connected with disturbed lipid metabolism and metabolic syndrome in humans." (PMID 24489111, 2014).
Allergy (2 papers, 2015 to 2016). An allergy is an immune response or reaction to substances that are usually not harmful. "The aim was to investigate if polymorphisms in the FADS gene cluster and the ELOVL2 gene were associated with the proportions of PUFAs in serum phospholipids from newborn infants and adolescents or with allergy development in a Swedish birth cohort." (PMID 27317923, 2016). "This is also the first study to analyze the association between allergy development and polymorphism in the ELOVL2 gene." (PMID 26633493, 2015). "In 211 subjects, we investigated whether polymorphisms in the FADS gene cluster and the ELOVL2 gene were associated with allergy or PUFA composition in serum phospholipids in a Swedish birth-cohort sampled at birth and at 13 years of age; allergy was diagnosed at 13 years of age." (PMID 26633493, 2015). "Polymorphisms in the ELOVL2 gene were nominally associated with decreased proportions of arachidonic acid in cord serum and decreased ratio of product over substrate in cord and adolescent serum, but not to the risk of developing allergic disease." (PMID 26633493, 2015).
COVID-19 (2 papers, 2023 to 2025). A disease caused by infection with severe acute respiratory syndrome coronavirus 2. "In addition, a recent study reported several significant differentially methylated sites associated with aging in COVID-19 patients including the ELOVL2 gene which accounts for several CpG sites in the Hannum epigenetic clock." (PMID 38017502, 2023). "For instance, the EpiAge metric, designed to capture age-related changes through specific CpG sites within the ELOVL2 gene, detects accelerated aging in less severe COVID-19 cases." (PMID 39853302, 2025).
male infertility (2 papers, 2019 to 2020). The inability of the male to effect fertilization of an ovum after a specified period of unprotected intercourse. "In mouse models, Elovl2 knockout has been shown to result in defective PUFA composition in the liver, serum and testis in association with male infertility and a reduced capacity to accumulate fat." (PMID 31619292, 2019).
renal carcinoma (2 papers, 2022 to 2025). A carcinoma arising from the epithelium of the renal parenchyma or the renal pelvis. "They showed that ELOVL2 ablation might suppress the production of docosahexaenoic acid (DHA) and LDs in renal cancer cells, suggesting that ELOVL2 overexpression may promote LD production through endogenous DHA production in RCC." (PMID 36430837, 2022).
acute coronary syndrome (1 paper, 2013). Signs and symptoms related to acute ischemia of the myocardium secondary to coronary artery disease. "The purpose of this study is to analyze the relationship between the polymorphisms of fatty acid desaturase 1 (FADS1), fatty acid desaturase 2 (FADS2), and elongation of very long-chain fatty acids-like 2 (ELOVL2) and acute coronary syndrome (ACS) in Chinese Han population." (PMID 23555103, 2013).
age (1 paper, 2020). A temporal measurement of the time period elapsed since an identifiable point in the life cycle of an organism. "Taken together, these data implicate ELOVL2‐specific activity as a potential functional target in age‐related eye diseases." (PMID 31943697, 2020).
benign meningioma (1 paper, 2022). A grade I, slowly growing meningioma. "In contrast, median expression scores for both FAM84B (6 vs 4, p ≤ .001) and ELOVL2 (9 vs 6, p < .001) were increased in high-grade as compared to benign meningiomas." (PMID 35445910, 2022).
benign prostatic hyperplasia (1 paper, 2025). A non-cancerous nodular enlargement of the prostate gland. "ELOVL2 exhibited the most pronounced upregulation in both PCa tissues and PCa cell lines compared to the benign prostatic hyperplasia (BPH) cell line BPH-1." (PMID 40552308, 2025).
chronic kidney disease (1 paper, 2025). Impairment of the renal function secondary to chronic kidney damage persisting for three or more months. "Similarly, research on chronic kidney disease has explored the role of ELOVL2 methylation in renal and cardiovascular events, indicating a possible interplay between this epigenetic marker and age-related health deterioration." (PMID 40244262, 2025).
colon tumors (1 paper, 2021). "Together with FADS2 and FADS1, levels of ELOVL2 and 5 have been found to be increased in colon tumors." (PMID 34206240, 2021).
cutaneous melanoma (1 paper, 2019). A primary melanoma arising from atypical melanocytes in the skin. "However, a single nucleotide polymorphism (SNP) at ELOVL2 rs3734398 was significantly associated with good prognosis in cutaneous melanoma." (PMID 31856871, 2019).
diabetic retinopathy (1 paper, 2014). "We previously showed that fatty acid elongases Elovl2 and Elovl4 are reduced in diabetic retinopathy, thus, we examined their daily expression in the retina and liver." (PMID 24736612, 2014). "Our previous study demonstrated that decreased expression levels of retinal fatty acid Elongases Elovl2, Elovl4 and Elovl6 play an important role in the pathogenesis of diabetic retinopathy." (PMID 24736612, 2014).
endothelial dysfunction (1 paper, 2025). In vascular diseases, endothelial dysfunction is a systemic pathological state of the endothelium (the inner lining of blood vessels) and can be broadly defined as an imbalance between vasodilating and vasoconstricting substances produced by (or acting on) the endothelium. "The observed alterations in lipid metabolism can be attributed to the upregulation of stearoyl-CoA desaturase-1 (SCD1) and the impairment of FADS1/2 and ELOVL2/5 activity, which in turn give rise to conditions conducive to inflammation, endothelial dysfunction, and plaque instability." (PMID 40564102, 2025).
fibrosis (1 paper, 2025). the formation of excess fibrous connective tissue in an organ or tissue in a reparative or reactive process. "Five variable multi-omics analysis provided more granular understanding of the core differences in expression between groups, with ELOVL2, LIPK, LAMA3, and lncRNAs partnered with UHRF1BP1L and S1PR1 found to most reliably discriminate the control and fibrosis groups." (PMID 40040391, 2025).
gastric cancer (1 paper, 2023). A primary or metastatic malignant neoplasm involving the stomach. "The mRNA levels of RAI14, GUCY1A2, CNGB3, FJX1, FZD2, ELOVL2, and GDPD4 were all expressed upregulated in gastric cancer tissues, except for CXCL13, whose expression level was not significantly different between gastric cancer tissues and normal cell lines." (PMID 36823639, 2023).
growth disorder (1 paper, 2022). "Eleven of the 22 analysed CpGs in the genes PDE4C, ELOVL2 and RPA2 exhibited significant differences between young, healthy individuals and age- and sex-matched individuals with growth disorders." (PMID 35551445, 2022).
Hepatitis (1 paper, 2018). Inflammation of the liver. "The decreased levels of PUFA in hepatitis patients in comparison to controls, which specifies the reduced activities of ELOVL2, ELOVL4 and ELOVL5 enzymes." (PMID 29506525, 2018).
macular degeneration (1 paper, 2020). Loss of vision in the central portion of the retina (macula), secondary to retinal degeneration. "The finding that loss of ELOVL2 activity results in early accumulation of sub‐RPE deposits strengthens the relationship between PUFAs and macular degeneration." (PMID 31943697, 2020).
meningioma (1 paper, 2022). A generally slow growing tumor attached to the dura mater. "As the first study so far, we revealed a brisk ELOVL2 expression in meningiomas, which was additionally increased in high-grade as compared to benign lesions." (PMID 35445910, 2022). "In conclusion, this is the first study reporting the expression of the oncogenes TRIM58, FAM84B, ELOVL2, and DIO3 in meningiomas and correlations with histology and prognosis." (PMID 35445910, 2022). "Expression of the corresponding onco- and tumor suppressor genes TRIM58, FAM84B, ELOVL2, MAL2, LMO3, and DIO3 were analyzed and scored by immunohistochemical staining and RT-PCR in samples of 111 meningioma patients." (PMID 35445910, 2022). "Recent in vitro analyses revealed a dose-dependent efficiency of DCT also in high-grade meningiomas, with specific DNA demethylation of several onco- or tumor suppressor genes (TRIM58, FAM84B, ELOVL2, MAL2, LMO3, DIO3), which have been hardly investigated in meningiomas yet." (PMID 35445910, 2022).
Papillary thyroid carcinoma (1 paper, 2021). "For example, the DNA methylation patterns of UBAC2 and ELOVL2, which are highly correlated with Chromosomal instability, provide potential prognostic value in Papillary thyroid carcinoma." (PMID 33550277, 2021).
retinal degeneration (1 paper, 2014). Degeneration of the retina. "Group (b) was very small with only 9 genes, and it did not make a cluster of functionally related GO terms, although 6 of 9 genes were annotated as causal genes for retinal degeneration (Abca4, Elovl2, Fscn2, Nxnl1, Pde6c, and Pde6h)." (PMID 24747725, 2014).